OR5K2 (olfactory receptor family 5 subfamily K member 2)
Description:
Odorant receptor.
Synonyms: OR3-9
Tractability: Antibody: UniProt places it where antibodies can reach, with medium confidence; UniProt predicts a signal peptide or a membrane-spanning region; its Gene Ontology location is reachable by antibodies, with medium confidence.
Gene: Protein-coding gene on chromosome 3 (98,497,681 to 98,498,631, forward strand). Ensembl gene ENSG00000231861.
Subcellular location: Cell membrane
Pathways (Reactome):
Sensory Perception: Expression and translocation of olfactory receptors
Gene Ontology:
Molecular function: protein binding; odorant binding; olfactory receptor activity; G protein-coupled receptor activity
Biological process: sensory perception of smell; detection of chemical stimulus involved in sensory perception of smell; G protein-coupled receptor signaling pathway
Cellular component: plasma membrane; membrane
Genetic constraint (gnomAD): Missense variants: 353 observed, 334.94 expected, observed/expected ratio (o/e) 1.05, 90% interval 0.96 to 1.15. Synonymous variants: 106 observed, 120.86 expected, observed/expected ratio (o/e) 0.88, 90% interval 0.75 to 1.03.
Homologues: Orthologues: macaque OR5K2 (94% identical), chimpanzee OR5K2 (93% identical), dog OR5K1 (82% identical), mouse Or5k1 (81% identical), mouse Or5k1b (77% identical). Paralogues in human: OR5K1 (92% identical), OR5K4 (70% identical), OR5K3 (70% identical), OR5H6 (51% identical), OR5H2 (50% identical), OR5H14 (49% identical), OR5H15 (49% identical), OR5H1 (48% identical), OR5AC2 (48% identical), OR5B12 (47% identical), OR8B12 (46% identical), OR9G4 (46% identical), and 84 more.